SPATA18 (spermatogenesis associated 18)
Description:
Key regulator of mitochondrial quality that mediates the repairing or degradation of unhealthy mitochondria in response to mitochondrial damage. Mediator of mitochondrial protein catabolic process (also named MALM) by mediating the degradation of damaged proteins inside mitochondria by promoting the accumulation in the mitochondrial matrix of hydrolases that are characteristic of the lysosomal lumen. Also involved in mitochondrion degradation of damaged mitochondria by promoting the formation of vacuole-like structures (named MIV), which engulf and degrade unhealthy mitochondria by accumulating lysosomes. The physical interaction of SPATA18/MIEAP, BNIP3 and BNIP3L/NIX at the mitochondrial outer membrane regulates the opening of a pore in the mitochondrial double membrane in order to mediate the translocation of lysosomal proteins from the cytoplasm to the mitochondrial matrix. Binds cardiolipin. May form molecular condensates (non-membrane-bounded organelles) within mitochondria that compartmentalize and promote cardiolipin metabolism.
Synonyms: MIEAP; FLJ32906; SPETEX1
Tractability: PROTAC: ubiquitination databases record sites on it.
Gene: Protein-coding gene on chromosome 4 (52,051,304 to 52,097,302, forward strand). Ensembl gene ENSG00000163071.
Subcellular location: Cytoplasm, cytosol; Mitochondrion outer membrane; Mitochondrion matrix; Cytoplasm, cytosol (Isoform 1); Cytoplasm, cytosol (Isoform 2)
Subcellular location (Human Protein Atlas): Mitochondria; Cytosol; Nucleoplasm
Gene Ontology:
Molecular function: cardiolipin binding; identical protein binding; molecular condensate scaffold activity; protein binding
Biological process: mitochondrial protein catabolic process; mitophagy by internal vacuole formation; positive regulation of cardiolipin metabolic process
Cellular component: cytoplasm; cytosol; intracellular membrane-bounded organelle; mitochondrial matrix; mitochondrial outer membrane; mitochondrion
Genetic constraint (gnomAD): Loss-of-function variants: 48 observed, 63.18 expected, observed/expected ratio (o/e) 0.76, 90% interval 0.6 to 0.97. The upper end of that interval is the gene's LOEUF score, 0.97, which puts it in group 4 of 6, group 1 being the genes least tolerant of losing a copy. Missense variants: 693 observed, 671.99 expected, observed/expected ratio (o/e) 1.03, 90% interval 0.97 to 1.1. Synonymous variants: 228 observed, 243.24 expected, observed/expected ratio (o/e) 0.94, 90% interval 0.84 to 1.05.
Homologues: Orthologues: chimpanzee SPATA18 (98% identical), macaque SPATA18 (95% identical), pig SPATA18 (79% identical), rabbit SPATA18 (78% identical), mouse Spata18 (71% identical), rat Spata18 (71% identical), dog SPATA18 (69% identical), tropical clawed frog spata18a (50% identical), zebrafish spata18 (48% identical), tropical clawed frog spata18b (48% identical), Drosophila melanogaster CG11498 (16% identical).
Diseases named in the same sentence as SPATA18 in open-access papers:
SPATA18 is named in the same sentence as 33 diseases in open-access papers, as found by Europe PMC text mining. Sharing a sentence is not in itself a finding about the gene and the disease. The quoted sentences say what the papers report.
breast carcinoma (8 papers, 2017 to 2024). "Moreover, high expression of the SPATA18 gene is associated with good prognosis in ER+ breast cancer." (PMID 38182927, 2024). "Probably, non-genetic factors may account for changes in the expression of these proteins, because, according to TCGA, KIF14, EZR, and SPATA18 genes are very rarely mutated in breast cancer (less than 1%)." (PMID 32679794, 2020). "Spermatogenesis-related protein 18 (SPATA18) is involved in mitochondrial quality control and induces mitochondrial-directed apoptosis in breast cancer cells." (PMID 36330441, 2022). "However, SPATA18 was reported to suppress growth of murine intestinal tumor and human breast cancer via mitochondrial quality control." (PMID 34858848, 2021). "Other stromal genes dysregulated in AA women with breast cancer include Ras association domain-containing protein 1 (RASSF1A), Retinoic acid receptor beta (Retinoic acid receptor beta), Spermatogenesis associated 18 (SPATA18), and Sons of sevenless drosophila homolog 1 (SOS1)." (PMID 32824813, 2020).
thyroid cancer (4 papers, 2022 to 2025). "It is also worth mentioning that there is evidence that in thyroid cancer, the expression of the SPATA18 gene is low, which leads to an increase in the number of abnormal mitochondria, in the level of reactive oxygen species, and in the mtDNA/nDNA ratio and to acidification of the cytoplasm." (PMID 39682560, 2024).
colorectal cancer (3 papers, 2019 to 2022). A primary or metastatic malignant neoplasm that affects the colon or rectum. "In the present study, 268 primary colorectal cancers (CRCs) were evaluated immunohistochemically for SPATA18 expression to assess its predictive utility and its association with cellular proliferation activity." (PMID 35269894, 2022). "SPATA18 expression can predict favorable clinical outcomes in colorectal cancer." (PMID 36330441, 2022).
intestinal tumors (3 papers, 2015 to 2022). "Moreover, intestinal tumors in Spata18-deficient ApcMin/+ mice showed more advanced grades of adenomas and adenocarcinomas than Spata18-WT ApcMin/+ mice." (PMID 35269894, 2022). "When Spata18 knock out mice were crossed with ApcMin/+ mice, which are known to develop multiple benign tumors in the small intestine, Spata18-deficient ApcMin/+ mice showed a much shorter lifespan with a higher number and size of intestinal tumors compared with Spata18-WT ApcMin/+ mice." (PMID 35269894, 2022).
asthenospermia (1 paper, 2023). "The observed downregulation of SPATA18 in the asthenospermia group highlights the crucial role of this gene in sperm motility and fertility." (PMID 37799407, 2023).
bladder carcinomas (1 paper, 2022). "In contrast, bladder carcinoma showed higher risk in SPATA18-expressing tumors (HR = 1.43)." (PMID 35269894, 2022). "In contrast, bladder carcinomas indicated a higher risk in SPATA18-high tumors with unknown mechanisms." (PMID 35269894, 2022).
cardiomyopathy (1 paper, 2021). A disease of the heart muscle or myocardium proper. "Those authors identified genes implicated in cardiac calcium homeostasis (PDE3B), oxidative stress response (FDXR and SPATA18), and the etiology of cardiomyopathy (SGCD, BBC3 and GDF15)." (PMID 33820914, 2021).
male infertility (1 paper, 2015). The inability of the male to effect fertilization of an ovum after a specified period of unprotected intercourse. "We observed differential expression of a number of transcripts, such as PRM1, SPATA18, TNP1, EIF4G2, CANX, RANBP9, TCP11, which have previously been associated with male infertility." (PMID 25973848, 2015).
osteosarcoma (1 paper, 2021). A usually aggressive malignant bone-forming mesenchymal neoplasm, predominantly affecting adolescents and young adults.
Tinnitus (1 paper, 2023). Tinnitus is an auditory perception that can be described as the experience of sound, in the ear or in the head, in the absence of external acoustic stimulation. "Spata18 can act as a potential target for tinnitus treatment because it is involved in the autophagy process, which undergoes the anti-tinnitus effect of melatonin." (PMID 37190538, 2023).
ZIKV infection (1 paper, 2018). "This adverse effect of ZIKV infection on SPATA18 expression could be significantly alleviated by EBS treatment (ZIKV vs. ZIKV+EBS)." (PMID 29447264, 2018).
tumor (8 papers, 2015 to 2025). "SPATA18 expression was associated with tumor size (p < 0.0001), histological differentiation (p = 0.0017), and lymph node metastasis (p = 0.00039)." (PMID 35269894, 2022). "Univariate analyses revealed significant associations between SPATA18 expression and tumor size (p < 0.0001), histological differentiation (p = 0.0017), and lymph node metastasis (p = 0.00039)." (PMID 35269894, 2022). "Spermatogenesis associated 18 (SPATA18) and EF-hand domain family member D1 (EFHD1), as opposed to SPOCK1, GTSE1 and ADAM12, are two tumor suppressors both involved in mitochondria functions." (PMID 37370817, 2023).
cancer (5 papers, 2021 to 2023). A tumor composed of atypical neoplastic, often pleomorphic cells that invade other tissues.
SPATA18 also shares sentences with these, for which no sentence is quoted: adenocarcinoma (1 paper); adenoma (1); anemia (1); Azoospermia (1); clear cell renal cell carcinoma (1); colon cancers (1); Colonic adenocarcinoma (1); endometrial carcinoma (1); follicular adenomas (1); gastric cancer (1); Globozoospermia (1); head and neck squamous cell carcinoma (1); hemorrhage (1); infection (1); lung adenocarcinoma (1); papillary renal cell carcinoma (1); papillary thyroid cancers (1); sarcoma (1); thyroid (1); thyroid oncocytic adenomas (1).